CST3 (cystatin C)
Diseases named in the same sentence as CST3 in open-access papers (continued):
Sharing a sentence is not in itself a finding about the gene and the disease.
type 2 diabetes (70 papers, 2012 to 2026). "Similar to cystatin C, plasma galectin-9 has also been shown to be associated with aging-related comorbidities such as type 2 diabetes, atherosclerotic stroke, and coronary artery disease in various studies." (PMID 37569647, 2023). "A 15 years cohort study demonstrated that, after controlling for multiple covariates, baseline serum cystatin C was significantly associated with 15 years cumulative incidence of type 2 diabetes (OR per log of cystatin C unit 2.19, 95% CI 1.02–4.68)." (PMID 37056689, 2023). "Increased serum levels of glycated albumin, cystatin C, and adipokine C1q tumor necrosis factor related protein 1 were associated with poor coronary collateralization in type 2 diabetic patients with stable coronary artery disease and CTO." (PMID 29422093, 2018). "Regarding NGFR gene rs734194 SNP, its minor allele showed association with TOAST small artery occlusion (p = 0.02), Type 2 diabetes (p = 0.019), height (p = 0.019), serum cystatin C (p = 0.016)." (PMID 29499660, 2018). "Similarly, the loci specific to cystatin C were associated with GWAS traits such as high-density lipoprotein (HDL) cholesterol levels, consistent with cystatin C's known associations with dyslipidemia and diabetic nephropathy in patients with type 2 diabetes." (PMID 39927731, 2025). "Cystatin C may be a further link between Alzheimer’s and type 2 diabetes, since polymorphisms were found in both conditions, and cystatin C binds amyloid β and fosters aggregation of amyloid β40 and amyloid β42 at certain concentrations." (PMID 39683565, 2024). "Cystatin C was positively associated with age, male sex, waist circumference, and type 2 diabetes." (PMID 32097414, 2020). "Study has found that elevated levels of cystatin C may increase the risk of type 2 diabetes." (PMID 37056689, 2023). "Our study had focused on many markers such as serum cystatin-C and urinary hemeoxygenase to be screened as early indicators of DN in long-term type 2 diabetic patients." (PMID 37002266, 2023). "Previous studies have reported a positive correlation between adiponectin and cystatin C in patients with type 2 diabetes." (PMID 36359307, 2022). "Cystatin C also is the fifth most influential biomarker in the diabetes type 2 predictor for both sexes, while these predictors are dominated by the standard biomarker glycated haemoglobin." (PMID 34209487, 2021). "Serum cystatin C was shown previously to be a useful marker of early renal impairment in type 2 diabetic patients." (PMID 34202668, 2021). "This cross-sectional study including 1609 Chinese type 2 diabetic patients at the first time investigated the relationship between serum cystatin C levels and lower extremity arterial disease in T2DM population." (PMID 23843968, 2013). "Their study suggested that cystatin C may be more effective than creatinine in detecting early renal impairment in patients with type 2 diabetes." (PMID 39502964, 2024). "We examined the level of serum C-Man-Trp in patients with type 2 diabetes, and found that the level of serum C-Man-Trp is significantly correlated with that of the creatinine or cystatin C, indicating that serum C-Man-Trp is useful to estimate the renal function in patients with type 2 diabetes." (PMID 34500691, 2021). "Thus, the utility of eGFR in type 2 diabetes is still unclear, in particular, those new equations based on cystatin-C or the combination of creatinine and cystatin-C." (PMID 31561432, 2019). "This suggests that anti-angiogenic cystatin C may be an indicator of coronary collateral formation in type 2 diabetic patients with stable coronary artery disease and CTO." (PMID 29422093, 2018). "Therefore, cystatin C was believed to be a sensitive biomarker for screening out PAD in the type 2 diabetic populations." (PMID 23843968, 2013).
type 2 diabetes (continued). "The aim of this study was to evaluate the association of cystatin C, CD26, and CD14 proteins in serum exosomes from patients with Type 2 Diabetes (T2D), metabolic syndrome (MetS), and atherogenic index of plasma (AIP)." (PMID 35846887, 2022). "As previously reported in type 2 diabetes and observed in our study, the correlations between GFR and either creatinine or cystatin C were stronger in patients with decreased GFR compared to those with normal GFR." (PMID 39502964, 2024). "In another study carried out by our research group, u-Cystatin C/u-creatinine was found to be significantly higher in the sepsis-related AKI group than in patients with chronic hypertension and those with type 2 diabetes." (PMID 37836706, 2023). "In patients with type 2 diabetes, serum VEGF-B level was positively correlated with triglyceride, serum creatinine and cystatin C while negatively correlated with HDL-C and eGFR." (PMID 35399943, 2022). "Therefore, this study was conducted to explore the role of cystatin C in multivessel coronary artery disease in type 2 diabetes patients with normal renal function and to determine whether cystatin c influences multivessel coronary artery disease independent of traditional risk factors." (PMID 32306911, 2020). "Serum cystatin C concentrations were measured by using particle-enhanced immunonephelometric assays before coronary angiography in 135 consecutive type 2 diabetes patients and 179 nondiabetic patients with normal renal function." (PMID 32306911, 2020). "The results of the present study are also in line with our previous findings that cystatin C-based equation was superior to creatinine-based formula for estimating GFR and identifying poor collateralization in type 2 diabetic patients with coronary artery disease." (PMID 26402227, 2015).
Stroke (65 papers, 2011 to 2026). Sudden impairment of blood flow to a part of the brain due to occlusion or rupture of an artery to the brain. "Subgroup analyses stratified by clinical and demographic characteristics revealed heterogeneous associations between cystatin C levels and stroke risk." (PMID 40941489, 2025). "Serum cystatin C concentrations exhibited a graded positive association with stroke morbidity across multivariable-adjusted models." (PMID 40941489, 2025). "EGFR and elevated cystatin C levels are linked to higher stroke risk, while elevated UA levels are associated with both insulin resistance and poor stroke outcomes." (PMID 40667444, 2025). "Cohort studies further corroborate these findings, reporting associations between elevated cystatin C and increased post-stroke mortality." (PMID 40941489, 2025). "Below the 1.24 mg/L threshold, each 0.1 mg/L increase in cystatin C conferred 13.84-fold higher stroke risk (95% CI: 7.11–27.04), demonstrating exponential risk elevation in the subthreshold range." (PMID 40941489, 2025). "Subsequently, 11,598 adults were retained for mortality endpoint analyses, which focused on the longitudinal association between cystatin C and stroke mortality, using cause-specific weighted multivariable Cox models and ratios (HRs)." (PMID 40941489, 2025). "Among patients with stroke, all-cause mortality risk increased with higher cystatin C levels (Q4 HR = 1.35, 0.73–2.51; p = 0.338), although the trend was not statistically significant (p for trend = 0.134)." (PMID 40941489, 2025). "In fully adjusted models, elevated cystatin C was associated with a 2.03-fold higher odds of stroke (OR = 2.03, 95% CI: 1.46–2.82; p < 0.001)." (PMID 40941489, 2025). "Where logistic regression suggested uniform risk elevation, RCS revealed that cystatin C < 1.24 mg/L carries exponentially increasing stroke risk per unit increment—a finding with profound implications for early intervention." (PMID 40941489, 2025). "While observational studies have associated elevated cystatin C with an increased risk of stroke, the prognostic value of cystatin C for cardio-cerebrovascular mortality remains inconclusive due to methodological heterogeneity." (PMID 40941489, 2025). "Subthreshold cystatin C levels (<1.24 mg/L) are associated with an amplified risk of stroke, while suprathreshold concentrations exhibit attenuated effects." (PMID 40941489, 2025). "Compared with people of the first quartile of cystatin C, those in the last quartile had the highest risk of stroke (OR, 1.380; 95% CI, 1.046–1.825) when cystatin C was assessed as quartiles." (PMID 38681764, 2024). "The positive associations between cystatin C and stroke or cardiovascular risk have also been reported among the European, US, Chinese, and multi-ethnic populations." (PMID 38681764, 2024). "Mendelian randomization estimates for the association of cystatin C with stroke using the inverse variance-weighted (IVW) model and Pleiotropy RESidual Sum and Outlier (PRESSO)." (PMID 38681764, 2024). "Overall, the causal relationship between cystatin C and stroke or its subtypes warrants more evidence from both epidemiologic and genetic perspectives." (PMID 38681764, 2024). "Our aim was to assess the link between cystatin C levels, both measured and genetically predicted, and stroke risk." (PMID 38681764, 2024). "The debate over the causal and longitudinal association between cystatin C and stroke in older adults persists." (PMID 38681764, 2024). "Cystatin C is a potential indicator for stratifying the risk of stroke compared to serum creatinine." (PMID 38681764, 2024). "The causal association of cystatin C with stroke remained after removing three outliers (pleiotropic SNPs) using MR-PRESSO [OR, 1.128 (95% CI, 1.058–1.203); p < 0.001]." (PMID 38681764, 2024). "In the current analysis using a national cohort, we found that cystatin C level is significantly associated with new-onset stroke event among the Chinese population." (PMID 38681764, 2024).
Stroke (continued). "Studies have shown that renal function biomarkers such as urinary microalbumin, cystatin C, and creatinine are associated with higher stroke recurrence rates and poorer prognosis." (PMID 39540824, 2024). "In summary, this study supported the causal association between serum cystatin C level and the risk of stroke, combining the national cohort design and two-sample MR analysis." (PMID 38681764, 2024). "The trends of increased stroke risk concordant with a higher cystatin C level were similar across male and female participants." (PMID 38681764, 2024). "In the fully adjusted model, there was a positive association between serum cystatin C concentration and new-onset stroke." (PMID 38681764, 2024). "A cross-sectional study reported that serum cystatin C levels were associated with higher risks of both hemorrhagic and ischemic stroke and the prognosis of stroke patients." (PMID 38681764, 2024). "Another cross-sectional study reported that higher cystatin C levels were directly associated with an increased proportion of stroke, including hemorrhagic and ischemic stroke." (PMID 38681764, 2024). "After adjusting for confounding factors, compared to those in the first quartile of cystatin C, those in the last quartile had the greatest risk of stroke incidence [odds ratio (OR), 1.380; 95% confidence interval (CI), 1.046–1.825]." (PMID 38681764, 2024). "This national cohort study suggests that higher serum cystatin C is associated with an increased risk of total stroke, which is further supported by Mendelian randomization." (PMID 38681764, 2024). "The Mendelian randomization analysis showed that a genetically predicted cystatin C level was positively associated with total stroke (OR by inverse variance-weighted method, 1.114; 95% CI, 1.041–1.192)." (PMID 38681764, 2024). "Our study confirms the significant association between cystatin C and stroke, but further studies are needed to elucidate the mechanisms involved." (PMID 37155257, 2023). "Higher cystatin C levels were significantly associated with stroke risk in the overall population (B = 4.205, 95% CI = 3.180–5.230, p < .001), in men (B = 1.872, 95% CI = 0.465–3.278, p = .009) and in women (B = 4.029, 95% CI = 2.252–5.806, p < .001)." (PMID 37155257, 2023). "Cystatin C was associated with new-onset stroke (HR: 1.19; 95% CI: 1.14, 1.25), thereby confirming our findings." (PMID 37155257, 2023). "To find out if cystatin C can be a potential biomarker of stroke, we analysed the association between serum cystatin C level and stroke risk." (PMID 37155257, 2023). "Among CVDs, plasma cystatin C were associated with stroke (1.10, 1.08–1.11) and MI (1.08, 1.07–1.10)." (PMID 37663661, 2023). "In the Cardiovascular Health Study with an 8-year follow-up, cystatin C proved to be a significant predictor of all-cause and cardiovascular death (myocardial infarction and stroke)." (PMID 35453881, 2022). "MR uses genetic variation as a natural experiment to estimate causality in observational data and has, for example, been used to detect a causal effect of cystatin C on risk of stroke." (PMID 34413458, 2022). "Our previous study showed higher levels of baseline serum cystatin C associated with an increased risk of long-term stroke in elderly patients with OSA." (PMID 36117703, 2022). "Previous studies have shown that various CKD parameters, such as eGFR, albuminuria, and cystatin C, were associated with the outcomes of stroke." (PMID 36070300, 2022). "Increased serum cystatin C levels have also been shown to be associated with subclinical atherosclerosis and recurrent stroke." (PMID 35307027, 2022). "We also found direct associations of all 5 markers with myocardial infarction (MI) risk, and of GDF-15, NT-proBNP, CRP and cystatin-C with stroke risk." (PMID 34935094, 2022).
Stroke (continued). "A recent meta-analysis of over 22,000 participants from 14 studies showed that higher cystatin C levels were strongly and independently associated with specific endpoints such as stroke, myocardial infarction, and heart failure." (PMID 35208542, 2022). "Several cross-sectional studies have shown that Cystatin C (Cys C) is an independent risk factor for cerebrovascular diseases and levels of Cys C are significantly higher in stroke patients than in healthy individuals." (PMID 34260548, 2021). "Accumulating evidence has revealed that obstructive sleep apnea (OSA) and Cystatin C (Cys-C) play important roles in the increased risk of stroke." (PMID 34975375, 2021). "Comparison of the values of normalized regression coefficients demonstrated that cystatin C was the most crucial risk factor for stroke, DVT, and AAA, and was superseded by glycated hemoglobin only in the CAD model." (PMID 32726343, 2020). "While cystatin C had improved risk stratification for stroke, GFR was a better predictor of bleeding, so both markers have the potential to improve risk prediction in patients with AF." (PMID 25215263, 2014). "In the same population, rising cystatin C levels were independently associated with increased rates of stroke or systemic embolism, mortality, and major bleeding." (PMID 25215263, 2014). "Other researchers found that elderly people with the highest quintile of cystatin C (1.29 mg/i) have a significantly elevated risk of death from cardiovascular causes, myocardial infarction, and stroke after multivariate adjustment." (PMID 22152087, 2011). "Mechanistically, cystatin C contributes to atherosclerosis by disrupting the balance between vascular proteases and antiproteases (e.g., inhibiting cysteine cathepsin activity), promoting plaque formation and instability, thereby increasing stroke risk." (PMID 40941489, 2025). "Therefore, the longitudinal and causal relationship of cystatin C with stroke in the general population needs more evidence." (PMID 38681764, 2024). "The association between cystatin C and stroke has been investigated in previous studies." (PMID 38681764, 2024). "Subgroup analysis of associations between baseline cystatin C quartile and the risk of stroke." (PMID 38681764, 2024). "Of note, the association between cystatin C and stroke seemed stronger among female participants, and the adjusted ORs for participants in the second, third, and fourth quartile were 1.505 (95% CI, 1.012–2.258), 1.643 (95% CI, 1.110–2.457), and 1.743 (95% CI, 1.158–2.647), respectively." (PMID 38681764, 2024). "However, a recent genetics study identified the loci associated with serum cystatin C among 363,228 individuals and hinted on the causal effect on stroke." (PMID 38681764, 2024). "Moreover, the two-sample MR analysis showed that higher genetically predicted cystatin C level is causally associated with a higher risk of stroke." (PMID 38681764, 2024). "The findings supported the causal association between cystatin C and total stroke." (PMID 38681764, 2024). "The findings suggested that cystatin C measurement should be incorporated into the assessment of stroke risk from the aspect of renal function, which could also be a possible target for improving cardiovascular health." (PMID 38681764, 2024). "Moreover, we employed a two-sample Mendelian randomization (MR) analysis to prevent any unmeasured confounding factors and reverse causation, thereby confirming the causal link between cystatin C and total stroke." (PMID 38681764, 2024). "In addition, other biomarkers such as serum fatty acid binding protein 4 (FABP4), serum CXCL12 levels, interleukin-37, and cystatin C have been reported to be associated with stroke recurrence." (PMID 37051146, 2023). "We aimed to determine whether the plasma cystatin C is a causal risk factor for cardiovascular events, stroke, myocardial infarction (MI), and cardiovascular disease (CVD) mortality by conducting Mendelian randomization (MR) designs." (PMID 37663661, 2023).